INS (insulin)
Diseases named in the same sentence as INS in open-access papers (continued):
Sharing a sentence is not in itself a finding about the gene and the disease.
Obesity (continued). "Rous-associated virus 7 (RAV-7), a retrovirus causing avian leukosis, can induce stunting and obesity in chickens, which is associated with hyperlipidemia and increased insulin levels, as well as immune dysregulation." (PMID 34795562, 2021). "For example, estrogen serves as a player in reducing risk for obesity, type II diabetes, and cardiovascular disease through effects on offspring insulin and leptin levels during gestation." (PMID 34828683, 2021). "While many lipid species are known to accumulate during obesity, ceramide metabolism is of great importance, because it is amongst the most metabolically pathogenic, since it directly interferes with insulin sensitivity." (PMID 34385976, 2021). "In obesity, excess visceral fat stored in the adipose tissue leads to hypertrophy of adipocytes and hypoxia which is associated with reduced insulin sensitivity accompanied by enhanced release of free fatty acid (FFA) into circulation." (PMID 34844584, 2021). "A recent Mendelian randomization analysis concluded that genetically predicted glucose and insulin-related traits were positively associated with breast cancer risk, results suggesting their role in the obesity-related etiology of breast cancer." (PMID 33738261, 2021). "In vivo studies in which CCR2 is genetically ablated or overexpressed show that these cells mediate obesity, obesity-induced hepatic steatosis, adipose tissue inflammation, insulin insensitivity, and the associated metabolic syndrome." (PMID 34613819, 2021). "The significant variables associated to insulin therapy were maternal age, obesity, previous GDM, altered FPG at OGTT, hypothyroidism, ART pregnancy, family history of DM." (PMID 33767671, 2021). "Other clues suggest that postprandial and obesity-associated falls in plasma ghrelin result from increased plasma insulin." (PMID 34473648, 2021). "In support of this, primary results from Intercept showed that weight loss in individuals with obesity was associated with improvement in insulin levels and reduction in Ki-67 expression in colorectal tissue, an established marker of cell proliferation." (PMID 33926456, 2021). "Obesity caused by the expansion of AT through adipogenesis is considered more metabolically favorable, as it is associated with preserved insulin sensitivity, while a greater degree of hypertrophy with less hyperplasia is associated with metabolic disorders." (PMID 34959926, 2021). "Diet rich in carbohydrates and saturated lipids is one of the major causes of obesity which affects insulin secretion and glucose metabolism in the cerebral region of the brain." (PMID 34183987, 2021). "Obesity is also associated with higher insulin and increased levels of many potential triggers of inflammation within adipose tissue, including bacterial components and proinflammatory cytokines." (PMID 33610548, 2021). "Short stature, increased weight gain, and early-onset obesity were observed at 2–3 years of age associated with elevated triglycerids, acanthosis nigricans, and increased hemoglobin A1C (HbA1C) suggesting insulin resistance." (PMID 34387706, 2021). "The underlying mechanisms by which cells become susceptible to obesity-related carcinogenesis includes genetic factors, insulin/IGF-I resistance, chronic low-grade inflammation and oxidative stress, change in adipokines, and alteration in the microbiome." (PMID 33827616, 2021). "There were 20 Slc genes with alteration confirmed in the liver of DIO mice and 15 of them were restored by MET, which was associated with improvement of insulin sensitivity and obesity." (PMID 34659115, 2021). "Obesity-induced inflammation is closely associated with IR in adipocytes, hepatocyte and other insulin-sensitive tissues through several pathways." (PMID 34844584, 2021).
Obesity (continued). "Particularly over the past decades, many reports have indicated that the NMU system plays an essential and direct role in regulating body weight, feeding behavior, energy metabolism, and insulin secretion, which are tightly linked to obesity pathophysiology." (PMID 33921859, 2021). "Thermogenesis is a bioenergetic process, which is associated with adiposity, obesity, insulin sensitivity, blood glucose concentration, and its related disorders." (PMID 34071903, 2021). "Other parameters associated with obesity, such as insulin levels at birth, showed that decreased insulin levels were associated with low concentrations of β-HCH in newborns." (PMID 34281107, 2021). "Similar to miR‐181b, miR‐30e levels were reduced in serum of mice with obesity induced by a high‐fat diet, suggesting an association with the insulin‐resistant‐associated obesity phenotype." (PMID 34118183, 2021). "Obesity, a known contributor to the risk of increased HbA1C, fasting glucose, and fasting insulin, has also been found to affect the development of periodontitis." (PMID 34899852, 2021). "Genetic mutations of GPR120 in both humans and mice are linked to obesity, increased fasting glucose levels, and insulin." (PMID 34943862, 2021). "Overexpression of this gene is associated with obesity in humans in addition to its effect on insulin sensitivity." (PMID 34972124, 2021). "Obesity and the associated inflammatory state in insulin-responsive tissues result in the release of pro-inflammatory cytokine that activates the stress-responsive MAPKs, p38 MAPK, and JNK." (PMID 34557866, 2021). "The fatty acids composition of the skeletal muscle membrane is correlated to peripheral response related to insulin and obesity, which are both susceptible to physical exercise." (PMID 34445440, 2021). "Fetal growth restriction and maternal malnutrition have been linked to the adult offspring’s increased risk of obesity and an impaired insulin sensitivity in humans and animal studies." (PMID 34203166, 2021). "It is established that over-accumulation of lipids and associated over-activation of lipid signalling pathways (lipotoxicity) contribute to loss of insulin secretion, beta cell toxicity and dysfunction, providing a link between obesity and T2D." (PMID 34203703, 2021). "Researchers have recently reported imbalances in intestinal microbiota, disease sensitivity, immune deficiencies, and, most specifically, obesity and resistance to insulin." (PMID 33802777, 2021). "In rodent models, both IUGR (maternal protein restriction, uterine artery ligation) and exposure to maternal diet-induced obesity is associated with impaired glucose-stimulated insulin secretion in islets of adult offspring." (PMID 34436455, 2021). "Increased irisin level has been proposed to be the result of the development of irisin resistance and serves as an adaptive response that compensates for the decreasing insulin sensitivity and metabolic disturbances associated with obesity." (PMID 34804606, 2021). "Another study employing a rat model of obesity observed that DNA hypermethylation was associated with reduced insulin sensitivity." (PMID 34068765, 2021). "Moderate weight loss (5% of body weight) can improve glycaemic control and insulin homeostasis and mitigate cardiovascular risk factors associated with overweight and obesity." (PMID 34484120, 2021). "Obesity-induced endothelial dysfunction, which is closely linked with insulin dysfunction, is attributed to ER stress." (PMID 34299638, 2021). "This is due to increased Cul4 neddylation, CRL4COP1 E3 assembly, and ubiquitylation of ETV5, an obesity-associated transcriptional suppressor of insulin secretion." (PMID 33911083, 2021). "Combined factors with age and obesity, elevated insulin levels are associated with activation of neuro-inflammatory signaling pathways and co-laterally increase amyloid-beta deposits in the brain causing AD." (PMID 34183987, 2021).
Obesity (continued). "In animal models, it has been shown that obesity, which is often associated with chronically elevated levels of insulin, leads to decreased FFA oxidation in the resting state." (PMID 33815283, 2021). "The objective of the study was to assess associations of the rs9939609 FTO allele to glucose tolerance, hepatic and total insulin sensitivity (IS) in individuals with obesity." (PMID 33684170, 2021). "Education was inversely but obesity and insulin users were positively associated with poor glycemic control." (PMID 33921201, 2021). "Through methods such as dietary restriction, exercise, and fasting, the first line of defence used against combating obesity is often weight loss, because it has been shown to improve outcomes such as insulin sensitivity, among other related co-morbidities." (PMID 33923531, 2021). "Increased plasma IL-6 levels are linked to obesity and reduced insulin sensitivity, via increased lipolysis, release of adiponectin and disruption of insulin signaling cascades." (PMID 33716966, 2021). "The accumulation of bone marrow‐derived macrophages (BMMs) in adipose tissue is an important cause of insulin resistance in adipose tissue under chronic inflammation resulting from obesity." (PMID 34647385, 2021). "Since hippocampus plays an important role in regulating spatial learning and memory processes, several studies have shown obesity associated altered insulin signaling leads to altered hippocampal function." (PMID 34690698, 2021). "Often associated with overweight and obesity, hyperglycemia is the result of resistance to insulin action combined with inadequate insulin secretion." (PMID 33467038, 2021). "A decreased capacity to increase fat oxidation when fatty acid availability or energy expenditure increases has been associated with obesity and lipid storage in skeletal muscle that impairs insulin signaling." (PMID 34209545, 2021). "The association of certain reproductive and insulin/obesity related SNPs in this study reflects the shared etiologies of T2DM and PCOS." (PMID 34784930, 2021). "Our findings confirm the inverse VitD relationship with some measures of obesity and insulin sensitivity in T2D, however this association was only observed in white subjects but not in those from black or Asian origin." (PMID 34380489, 2021). "Adiponectin has been shown to have anti-inflammatory properties and to increase tissue sensitivity to insulin, which is associated with its decreasing levels in obesity." (PMID 34208404, 2021). "Here, we describe a number of important intestinal immune cell-mediated mechanisms that facilitate the development of obesity-associated metabolic tissue inflammation, insulin resistance, intestinal hormone bioavailability, and glucose dysregulation." (PMID 33972511, 2021). "The deletion of NLRP3 or inhibition of caspase-1 in mice resulted in improved insulin sensitivity and ameliorated obesity-associated pathologies." (PMID 34070553, 2021). "Adipose tissue inflammation associated with obesity is known as a major cause for decreased insulin sensitivity in the case of T2D." (PMID 33927693, 2021). "Children with obesity have been linked to a 12-fold increase in fasting insulin concentration with abnormal levels of triglycerides, total cholesterol, LDL-c and HDL-c compared to children who are of healthy weight." (PMID 34125850, 2021). "In our study, the Slc genes were examined in the liver and alteration in their expression was associated with hepatic steatosis, hyperlipidemia, obesity and insulin sensitivity in the DIO mice." (PMID 34659115, 2021). "Non-alcoholic fatty liver disease (NAFLD) affects obesity-associated metabolic syndrome, which exhibits hepatic steatosis, insulin insensitivity and glucose intolerance." (PMID 34527673, 2021). "Accumulating evidence proposed that enhancement of the obesity-associated tumorigenesis can happen via inhibiting programmed cell death and insulin-IR-ERK1/2 signaling cascade activation." (PMID 34026558, 2021).
Obesity (continued). "In the insulin-resistant state associated with obesity, the insulin levels are high and have less variability from fasted to post prandial state." (PMID 34040583, 2021). "In recent years, growing evidence has linked changes in gut microbiota with insulin sensitivity and lipid metabolism, and is now a target for obesity treatment." (PMID 34366839, 2021). "Nevertheless, high levels of Lactococcus have been associated with obesity and fasting plasma insulin." (PMID 34444679, 2021). "Previous studies with in vivo models of obesity have demonstrated that reduced expression of miR-26a was associated with both insulin and glucose." (PMID 34690698, 2021). "By lowering FoxO1 acetylation and protein levels, SIRT1 prevents obesity caused by the insulin-unsusceptible vital nuclear location of FoxO1 in pro-opiomelanocortin (POMC) neurons in male mice." (PMID 33804729, 2021). "Independent lines of evidence from in vivo and in vitro studies demonstrate that reduced SCD1 activity, and SFAs improve glucose and energy metabolism, adiposity, insulin responses, and adipose inflammation associated with obesity." (PMID 34972124, 2021). "Compared with valproic acid, carbamazepine and topiramate have a reduced risk of altering insulin homeostasis and causing obesity." (PMID 34574891, 2021). "DCCT was one of the earliest studies demonstrating the association of intensive insulin therapy with weight gain and obesity." (PMID 34638531, 2021). "TNF-α is a classic proinflammatory factor that causes hypothalamic insulin and leptin resistance and is believed to be a contributor to the development of obesity." (PMID 34275474, 2021). "Sclerostin was positively associated with anthropometric indexes of obesity, and inversely with IR, namely homeostatic model assessment for peripheral insulin sensitivity (HOMA2%S) (r = −0.218; p = 0.045)." (PMID 33671861, 2021). "In humans and rodents, obesity is frequently associated with alterations in glucose homeostasis and insulin sensitivity." (PMID 34527673, 2021). "Circulating levels of adiponectin are inversely associated with glycemia, insulin sensitivity and inflammation and is largely recognized as a marker for obesity and metabolic-related diseases." (PMID 34652617, 2021). "This is evident as two hallmarks of obesity, excessive food intake and a reduced stimulation of postprandial insulin secretion by gut hormones, are linked to impaired gut function." (PMID 34552271, 2021). "Insulin and leptin resistance, as well as dysregulation of related pathways, are associated with obesity and metabolic disorders and central nervous system (CNS) dysfunctions." (PMID 34795562, 2021). "The main metabolic comorbidity of obesity is type-2 diabetes that occurs when body tissues become resistant to insulin and is estimated to be the seventh leading cause of death." (PMID 34201257, 2021). "Fasting insulin concentrations differed between ethnic and BF% groups with an increased risk of hyperinsulinemia in Pacific women and women with obesity." (PMID 34122148, 2021). "Insulin increases mitochondrial glucose oxidation and augments cell division in cells derived from obesity-associated tumors, including colon, breast and prostate cancer." (PMID 33987528, 2021). "The general obesity was associated with female sex and good glycaemic control, whereas abdominal obesity was associated with female sex and insulin treatment." (PMID 34394277, 2021). "In sum, these data demonstrate that reduced hepatic PLIN2 does not protect against the development of HFD-induced weight and fat mass gain or obesity-associated alterations in insulin–glucose homeostasis early in the progression of NAFLD." (PMID 33923083, 2021). "These metabolic results are thus consistent with RAGE deficiency being associated with improved glucose tolerance and insulin sensitivity in HFD-induced obesity in mice." (PMID 34686659, 2021).
Obesity (continued). "For instance, A gain of function of Adcy3 in mutagenized mice resistant to diet-induced obesity caused a reduction in both body weight, fat mass, insulin, and glucose levels compared to wild-type when subjected to high fat diet." (PMID 34177802, 2021). "✓Protection against obesity-associated cancers. ✓Reduces serum insulin levels inhibiting cell growth directly because insulin has been associated to cellular proliferation and inhibits apoptosis." (PMID 34062788, 2021). "Obesity can cause changes in the levels of insulin, IGF-1, leptin, adiponectin, steroid hormones and cytokines in the body, creating a favorable environment for the occurrence and development of tumors." (PMID 35083251, 2021). "Obesity is often associated with insulin-resistant glucose metabolism, and exercise training is a powerful tool for improving glucometabolic control." (PMID 32678867, 2021). "In conclusion, we describe the effects of Zfp217 deficiency on whole-body glucose and insulin levels and thermogenesis in a basal state and in diet-induced obesity." (PMID 34065474, 2021). "Endometrial cancer is strongly associated with obesity and dysregulation of metabolic factors such as estrogen and insulin signaling are causal risk factors for this malignancy." (PMID 34099314, 2021). "GlycA and GlycB biomarkers of inflammation, IR, insulin secretion and obesity have also been recently linked to PCOS." (PMID 33920227, 2021). "A partial reduction of plasma leptin level by leptin neutralizing antibody in obesity state improved leptin sensitivity and effectively led to weight loss and enhanced insulin sensitivity." (PMID 34084149, 2021). "The significant pathways associated with the common DEGs in depression and obesity are the type I interferon signaling pathway, cytokine-mediated signaling pathway, and insulin secretion involved in the cellular response to glucose stimulus." (PMID 34833079, 2021). "Several studies have shown that in obesity, infiltration of immune cells into the adipose tissue increases inflammation, which is associated with disturbed insulin signaling." (PMID 33921370, 2021). "Obesity leads to a significant expansion of adipose mass that radically influences adipose function, which causes disruption of insulin signaling in peripheral tissues including immune cells." (PMID 33390183, 2021). "Second, the NLRP3 inflammasome has been suggested to affect the regulation of adiposity and insulin sensitivity in the course of obesity, and mice deficient in NLRP3 were reported to be resistant to the development of obesity induced by a high-fat diet (HFD)." (PMID 35046893, 2021). "Combined, these data suggest that increased insulin and leptin in conjunction with decreased adiponectin in the context of obesity likely shifts the balance towards a more pathogenic/pro-inflammatory environment." (PMID 35822048, 2021). "The MT-RNR1 gene encodes MOTS-C protein that regulates insulin sensitivity and metabolic homeostasis and plays a protective role against diet-induced obesity." (PMID 33659027, 2021). "Recently, it has been reported that obesity-associated chronic low-grade inflammation is responsible for the decrease in insulin sensitivity." (PMID 34638553, 2021). "Unexpectedly, Treg-specific loss of IL-10 resulted in increased insulin sensitivity and reduced obesity in high-fat diet–fed male mice." (PMID 33351782, 2021). "Obesity is associated with an increased need for insulin and worse metabolic control, which increases the chances of developing atherosclerotic complications and possible hospitalization due to CVD." (PMID 34071142, 2021). "Recently, several studies have revealed that bariatric surgery including DJB can improve hepatic insulin sensitivity and reduce obesity-associated inflammation." (PMID 33869077, 2021). "With the occurrence and development of obesity, inflammatory immune cells infiltrated into adipose tissue and other metabolically active organs, causing inflammation and insulin resistance." (PMID 33541367, 2021).